TSLIG1 (tRNA splicing ligase complex subunit 1)
Description:
Activation factor of RTCB, the catalytic subunit of the tRNA-splicing ligase complex (tRNA-LC), which is involved in the enzyme-dependent maturation of intron-containing pre-tRNAs. Functions downstream of the tRNA-splicing endonuclease that removes introns, ligating the two generated halves via phosphodiester bond formation. Catalyzes the GTP-dependent activation of RTCB, both proteins forming a composite active site coordinating GTP and metal ions to enable the guanylylation of RTCB a prerequisite to undergo multiple catalytic cycles. Also required for the activation of RTCB in non-canonical, spliceosome-independent, cytoplasmic splicing of XBP1 mRNAs during the unfolded protein response (UPR). Upon endoplasmic reticulum (ER) stress, the endoribonuclease IRE1/ERN1 excises a short intron, generating free exon ends that are aligned by RNA-intrinsic, zipper-like stem-loop structures. These exon ends are then recognized and ligated by RTCB. This splicing event yields the active XBP1s transcription factor, which induces genes required to resolve protein folding defects in the endoplasmic reticulum.
Synonyms: ZBTB8OS; ARCH; ARCH2
Tractability: Small molecule: a structure with a bound ligand is known. Antibody: the Human Protein Atlas places it where antibodies can reach. PROTAC: ubiquitination databases record sites on it; its protein half-life has been measured.
Gene: Protein-coding gene on chromosome 1 (32,600,172 to 32,650,969, reverse strand). Ensembl gene ENSG00000176261.
Subcellular location: Cytoplasm; Nucleus
Subcellular location (Human Protein Atlas): Plasma membrane
Pathways (Reactome):
Metabolism of RNA: tRNA processing in the nucleus
Gene Ontology:
Molecular function: protein binding; protein guanylyltransferase activity; RNA ligase (GTP) activity
Biological process: IRE1-mediated unfolded protein response; mRNA splicing, via endonucleolytic cleavage and ligation; RNA splicing, via endonucleolytic cleavage and ligation; tRNA exon ligation; tRNA splicing, via endonucleolytic cleavage and ligation; tRNA processing
Cellular component: catalytic complex; cytoplasm; nucleus; tRNA-splicing ligase complex; nucleoplasm
Genetic constraint (gnomAD): Loss-of-function variants: 7 observed, 11.33 expected, observed/expected ratio (o/e) 0.62, 90% interval 0.35 to 1.16. The upper end of that interval is the gene's LOEUF score, 1.16, which puts it in group 5 of 6, group 1 being the genes least tolerant of losing a copy. Missense variants: 106 observed, 123.96 expected, observed/expected ratio (o/e) 0.86, 90% interval 0.73 to 1. Synonymous variants: 51 observed, 42.94 expected, observed/expected ratio (o/e) 1.19, 90% interval 0.95 to 1.5.
Homologues: Orthologues: chimpanzee ZBTB8OS (99% identical), macaque ZBTB8OS (99% identical), mouse Zbtb8os (96% identical), dog ZBTB8OS (95% identical), guinea pig ZBTB8OS (95% identical), pig ZBTB8OS (95% identical), rabbit ZBTB8OS (85% identical), rat Zbtb8os (82% identical), tropical clawed frog zbtb8os (76% identical), zebrafish zbtb8os (72% identical), Drosophila melanogaster Archease (43% identical), Caenorhabditis elegans arch-1 (37% identical).
Diseases named in the same sentence as TSLIG1 in open-access papers:
TSLIG1 is named in the same sentence as 4 diseases in open-access papers, as found by Europe PMC text mining. Sharing a sentence is not in itself a finding about the gene and the disease.
TSLIG1 shares sentences with these, for which no sentence is quoted: acute myeloid leukemia (1 paper); cervical cancer (1); malaria (1); thyroid cancer (1).